NHEJ1 (non-homologous end joining factor 1)
Description:
DNA repair protein involved in DNA non-homologous end joining (NHEJ); it is required for double-strand break (DSB) repair and V(D)J recombination and is also involved in telomere maintenance. Plays a key role in NHEJ by promoting the ligation of various mismatched and non-cohesive ends. Together with PAXX, collaborates with DNA polymerase lambda (POLL) to promote joining of non-cohesive DNA ends. May act in concert with XRCC5-XRCC6 (Ku) to stimulate XRCC4-mediated joining of blunt ends and several types of mismatched ends that are non-complementary or partially complementary. In some studies, has been shown to associate with XRCC4 to form alternating helical filaments that bridge DNA and act like a bandage, holding together the broken DNA until it is repaired. Alternatively, it has also been shown that rather than forming filaments, a single NHEJ1 dimer interacts through both head domains with XRCC4 to promote the close alignment of DNA ends (By similarity). The XRCC4-NHEJ1/XLF subcomplex binds to the DNA fragments of a DSB in a highly diffusive manner and robustly bridges two independent DNA molecules, holding the broken DNA fragments in close proximity to one other. The mobility of the bridges ensures that the ends remain accessible for further processing by other repair factors. Binds DNA in a length-dependent manner.
Synonyms: XLF; Cernunnos; FLJ12610; IMD124; MCOPCB13
Tractability: Small molecule: a structure with a bound ligand is known; it has a high-quality binding pocket. PROTAC: ubiquitination databases record sites on it; its protein half-life has been measured.
Gene: Protein-coding gene on chromosome 2 (219,069,355 to 219,160,869, reverse strand). Ensembl gene ENSG00000187736.
Subcellular location: Nucleus; Chromosome
Subcellular location (Human Protein Atlas): Nucleoplasm; Nucleoli fibrillar center
Pathways (Reactome):
DNA Repair: Nonhomologous End-Joining (NHEJ)
Gene Ontology:
Molecular function: DNA binding; DNA end binding; DNA polymerase binding; protein binding
Biological process: B cell differentiation; double-strand break repair via nonhomologous end joining; immunoglobulin V(D)J recombination; response to ionizing radiation; T cell differentiation; telomere maintenance; central nervous system development; positive regulation of ligase activity; double-strand break repair
Cellular component: chromosome; DNA-dependent protein kinase-DNA ligase 4 complex; fibrillar center; nonhomologous end joining complex; nucleoplasm; nucleus; site of double-strand break; DNA ligase IV complex
Genetic constraint (gnomAD): Loss-of-function variants: 20 observed, 35.62 expected, observed/expected ratio (o/e) 0.56, 90% interval 0.39 to 0.82. The upper end of that interval is the gene's LOEUF score, 0.82, which puts it in group 3 of 6, group 1 being the genes least tolerant of losing a copy. Missense variants: 300 observed, 349.69 expected, observed/expected ratio (o/e) 0.86, 90% interval 0.78 to 0.94. Synonymous variants: 145 observed, 136.11 expected, observed/expected ratio (o/e) 1.07, 90% interval 0.93 to 1.22.
Gene-disease validity (ClinGen):
ClinGen rates the evidence that NHEJ1 causes each of these diseases.
Cernunnos-XLF deficiency (autosomal recessive): Definitive. Cernunnos-XLF deficiency is a rare form of combined immunodeficiency characterized by microcephaly, growth retardation, and T and B cell lymphopenia.
Homologues: Orthologues: chimpanzee NHEJ1 (98% identical), macaque NHEJ1 (96% identical), pig NHEJ1 (82% identical), dog NHEJ1 (82% identical), guinea pig NHEJ1 (78% identical), rat Nhej1 (77% identical), mouse Nhej1 (74% identical), tropical clawed frog nhej1 (36% identical), zebrafish nhej1 (35% identical).